STAT3 (signal transducer and activator of transcription 3)
Diseases named in the same sentence as STAT3 in open-access papers (continued):
Sharing a sentence is not in itself a finding about the gene and the disease.
cancer (continued). "Differing research indicates that curcumin could regulate the STAT3 signaling pathway, with most research focusing on the role of STAT3 in cancers and its inhibition by curcumin." (PMID 36297027, 2022). "In several studies, STAT3 has significantly impacted cancer progression and related genes." (PMID 35566382, 2022). "Given that STAT3 is highly expressed in many malignant cancer cells, it may be possible to test the use of anti-STAT3 nanobody in the treatment of various cancers." (PMID 35933373, 2022). "Additionally, activating STAT3 signals promotes cell proliferation by promoting the progression of the cell cycle and inhibiting apoptosis in cancer." (PMID 36324680, 2022). "IL6/JAK/STAT3 signaling was reported to facilitate cancer progression in multiple cancer." (PMID 36276992, 2022). "Increased STAT3 signalling and upregulated levels of cyclin-D1 and cMYC expedite progression through the cell cycle, while pro-survival factors also suppress apoptosis in cancer cells." (PMID 36429126, 2022). "Therefore, STAT3 along with FUT family proteins are attractive targets for overcoming drug resistance in cancer." (PMID 35281907, 2022). "NF-kB-mediated secretion of IL-6 from immune cells in cancer originating from colon inflammation appears to activate NF-kB and STAT3-dependent signaling in epithelial cells of the gastric mucosa, such as upregulation of DNA methyltransferase activity and associated methylome changes." (PMID 35757000, 2022). "However, in cancer tissues, STAT3 is activated in an aberrant manner and is induced by certain cytokines." (PMID 35356799, 2022). "In addition, miR-769-5p inhibits cancer cell progression in OSCC by directly targeting the JAK1/STAT3 pathway." (PMID 36139534, 2022). "lncRNA RPSAP52 exerted anti-cancer effects via regulating miR-665/STAT3 in GC." (PMID 35322746, 2022). "STAT3 is well known as a transcription factor that defines gene expression programs in cancer." (PMID 34661759, 2022). "Biologically, STAT3 is a regulative factor for normal and cancer stem cells (CSCs)." (PMID 36061200, 2022). "Over 70% of human cancers are estimated to have aberrant STAT3 activity." (PMID 36176415, 2022). "STAT3’s activation by surface growth-stimulating receptors results in STAT3’s phosphorylation, dimerization, and subsequent transport to the nucleus, where it acts as a transcription factor for growth systems identified across cancers." (PMID 35626167, 2022). "Activation of the Jak2/Stat3 signaling promotes cell proliferation and cell stemness in cancer." (PMID 35600882, 2022). "STAT3, on the other hand, is involved in multiple pathways of cancer initiation and progression." (PMID 36145523, 2022). "After examining the hypothesis in a virtual system of predicting tumors, the findings suggest that ACN does inhibit STAT3 activation in human carcinoma cells." (PMID 36080130, 2022). "Herein, STAT3 promotes M2-type macrophages in the progression of carcinoma." (PMID 35585990, 2022). "Moreover, STAT3 signaling pathway positively regulates CyclinD1, Survivin, Bcl-2, Bcl-XL, and Mcl-1 to facilitate cancer cell cycle progression." (PMID 34179090, 2021). "Moreover, Qu’s role in cancer is reported through inhibitory activity against the STAT3 mechanism in diffuse big B-cell lymphoma cells." (PMID 33804548, 2021). "Some studies claimed that p38 MAPK and Stat3 signaling pathways could regulate cell cycle to control cancer cell proliferation." (PMID 34733155, 2021). "However, only limited data regarding the effect and molecular mechanism of action of ouabain on STAT3 in human cancer cells is available." (PMID 34277430, 2021).
cancer (continued). "With the same experimental design but in wild type mice, lycopene significantly exhibited anti-cancer property, mainly by inhibition of proinflammatory signaling as seen in a significant reduction in phosphorylation of NF-κB p65, STAT3, IL-6 and suppressed inflammatory foci." (PMID 34202203, 2021). "Aberrant STAT3 hyper-activation has been estimated to present in over 70% of human cancer and reported in almost all types of malignancies with a poor clinical outcome, and STAT3 together with its relative signaling pathway has long been recognized as a potential therapeutic target." (PMID 34502195, 2021). "Recent, some inhibitors of IL-6/STAT3 have been development, such as S31-201 or IL-6 neutralizing monoclonal antibody (IL-6 mAb), Madindoline A (Inhibits the dimerization of IL-6/IL-6R/gpl30 trimeric complexes), C188-9 and Curcumin (Inhibits STAT3 phosphorylation), etc. for treatment of cancers." (PMID 34976809, 2021). "Activators of STAT3 promote cancer growth through immuno-suppression." (PMID 34639131, 2021). "EVs derived from GC cells could induce polarization via the STAT3 pathway into M2-macrophages, which secrete IL-6 to promote malignancy of cancer cells." (PMID 33509150, 2021). "STAT3 is prevalent and active in a variety of human cancers." (PMID 33420372, 2021). "Thus, genetic or pharmacological approaches to suppress abnormally activated STAT3 are considered as treatments for cancers." (PMID 33669832, 2021). "Therefore, targeting STAT3 activation has been proposed as a therapeutic target in cancer treatment." (PMID 34502158, 2021). "Overexpression in five of the nine tissue types observed in our heatmaps for KPNB1 and STAT3 may be due to having identified four additional cancer types as significant comorbidities." (PMID 33924631, 2021). "STAT3 is constitutively active in many types of cancer with high frequency." (PMID 33925645, 2021). "Several clinical and preclinical studies with STAT3 inhibitors in cancer have led to the conclusion that, in order to improve the response to such drugs, one of the most prominent challenges is identifying patients who are likely to respond to the treatment based on predictive biomarkers." (PMID 34645505, 2021). "We next determined whether targeting STAT3 and the PI3K/mTOR pathway simultaneously blocked the feedback activation of STAT3 and sensitized PTEN-deficient cancer cells to BEZ235." (PMID 33431808, 2021). "By knocking out STAT3, cancer cells expressing FGFR1 V561M display restored sensitivity to AZD4547." (PMID 33568192, 2021). "Next, we tested the hypothesis that chemoattractants released from the PSCs stimulate cancer cells by activating the STAT3 pathway." (PMID 34440697, 2021). "Mechanistically, STAT3 promotes TNBC progression by cross-linking with phosphorylation of NF-κB p65, leading to its signaling pathway associated with metastatic gene expression of cancer or immune cells." (PMID 34638797, 2021). "Therefore, inhibition of STAT3 activation can be an effective method to reduce resistant cancer cell growth." (PMID 34577615, 2021). "Elevated GPR87 expression promotes cancer stem cell expansion by regulating the JAK2/STAT3 pathway." (PMID 34290570, 2021). "Napabucasin is an oral NAD(P)H:quinone oxidoreductase 1 bioactivatable agent that generates reactive oxygen species, is hypothesised to affect multiple oncogenic cellular pathways, including STAT-3, and is expected to result in cancer cell death." (PMID 34291369, 2021). "However, activating the NF-κB signaling pathway during cancer development and other pathogenic processes also involves phosphorylating AKT and STAT3 proteins." (PMID 34332611, 2021).
cancer (continued). "In addition to its established role as a transcription factor in cancer, STAT3 regulates mitochondrial function and gene expression through epigenetic mechanisms." (PMID 34079469, 2021). "Additionally, TRIM66, TRIM52 and TRIM14 also play an oncogenic role in CRC, since they are involved in cancer proliferation and metastasis through the regulation of STAT3 pathway expression." (PMID 33673719, 2021). "Also, STAT3 has been shown to inhibit autophagy, since STAT3 inhibitors can be potent inducers of autophagy in cancer cells." (PMID 33763424, 2021). "STAT3 signaling was reported to mediate drug resistance in various types of cancers." (PMID 33920736, 2021). "Besides TS oil, several other phytoconstituents belonging to the category of natural terpenoids has shown to inhibit the JAK/STAT pathway by inhibiting the phosphorylation of STAT3 in order to impede cancer cell growth." (PMID 34543231, 2021). "The clone formation assay corroborated the findings of the cell apoptosis assay, which also demonstrated that S3I-201 (STAT3 inhibitor) could rescue the radioresistance of cancer cells cultured with senescence-like CAF CM." (PMID 34877934, 2021). "Similarly, various receptor tyrosine kinase inhibitors have been previously shown to induce feedback activation of STAT3, which in turn promoted cancer cell survival and targeted therapy resistance." (PMID 34956861, 2021). "Furthermore, STAT3 is dispensable for the growth and survival of normal cells, which makes it a valuable cancer-specific target." (PMID 34944848, 2021). "Again, we highlighted the pivotal role of STAT3 in cancer progression and metastasis." (PMID 34936736, 2021). "It has been reported that activated STAT3/Bcl-2 pathway could inhibit autophagy, further promoting the proliferation of cancer cells." (PMID 34611143, 2021). "STAT3 may upregulate Bcl-2 expression to inhibit autophagy, further promoting the proliferation of cancer cells." (PMID 34611143, 2021). "Chemotherapy can stimulate HIF1, NFkB, SMAD, STAT3 and JNK/AP1 stress-linked signaling pathways in CAF, leading to a microenvironment which in turn can promote cancer proliferation and educate immune cells to an immunosuppressive phenotype, making cancer more invasive." (PMID 34359823, 2021). "Finally, the authors concluded that PKCε was an initial signal that induced STAT3 to sustain cancer invasiveness." (PMID 34440160, 2021). "Several recent studies have supported the crucial role of activated STAT3 in various cancers." (PMID 34834023, 2021). "It has been reported that the activation of the Akt/mTOR pathway could lead to the activation of STAT3 to participate in the maintenance of cancer stemness of NSCLC cells." (PMID 34681614, 2021). "Hyperactivation of STAT3 is widely confirmed in numerous cancers and related to poor prognosis." (PMID 34938816, 2021). "However, dysregulation of STAT3 is closely related to the survival, proliferation, and metastasis of cancer cells." (PMID 33546665, 2021). "Additionally, epithelial-to-mesenchymal transition, important in cancer cell invasiveness, metastatic potential, and cell detachment, is facilitated via IL-1, IL-6, and STAT3 signaling in chronic inflammation." (PMID 34988471, 2021). "The newly identified STAT3–TINCR–EGFR-feedback loop could serve as a potential therapeutic target for human cancer." (PMID 33446634, 2021). "IL-22 promotes cancer cell migration and invasion via STAT3, ERK, JNK, and Akt pathways." (PMID 34063828, 2021). "However, some FDA-approved compounds such as pyrimethamine and celecoxib were identified as STAT3 inhibitors through drug-repositioning screening, thus suggesting potential applications of these drugs for cancer therapy." (PMID 34685679, 2021). "STAT3 signaling plays an important role during cancer progression." (PMID 34941188, 2021). "Hence, FAP and CCL2 can be therapeutic targets because FAP develops cancer by activating CAF STAT3/CCL2 signaling." (PMID 34445235, 2021).
cancer (continued). "Moreover, a direct influence of activated STAT3 on the EMT transcription factor SNAIL is described in various cancer cell types." (PMID 34571833, 2021). "The cancerous tissues overexpress NF-κB and STAT3 to regulate many downstream genes—promoting cell survival and proliferation—and the crosstalk of these two transcription factors facilitates the establishment of cancer in vivo." (PMID 34299510, 2021). "While pharmacological inhibition of STAT3 has been an attractive target for anti-cancer therapies, it is possible that a systemic reduction in STAT3 activity may compromise intestinal barrier function and promote intestinal inflammation." (PMID 33673239, 2021). "In colon cancer, TRIM14 promoted cancer cell invasion by targeting the SPHK1/STAT3 pathway." (PMID 33982666, 2021). "Moreover, SIRT1 is involved in regulating the expression of STAT3 in various diseases, including cancer, diabetic kidneys and hepatic gluconeogenesis." (PMID 34044769, 2021). "Finally, our findings position PRMT5 as a critical regulator of gp130/STAT3 signaling to control the growth and development of human cancer, which provides an important mechanism for the oncogenic role of PRMT5." (PMID 34026434, 2021). "Although persist active STAT3 may induce cancer progression and gefitinib resistance, the mechanisms remained unclear." (PMID 34059647, 2021). "Hence, cancer cells over-expressing activated STAT3 are more likely to become resistant to apoptosis." (PMID 34268250, 2021). "Moreover, considerable evidence supports the crucial roles of STAT3 in human diseases, particularly in immune and inflammatory disorders, infections and cancer." (PMID 34302498, 2021). "Cancer cells also produce interleukin-6 (IL-6) to activate signal transducer and activator of transcription 3 (STAT3) to induce hypoxia-inducible factor-1alpha (HIF-1α), VEGF, and C-C motif ligand (CCL) 5 expression in lymphatic ECs (LECs) within premetastatic niches to promote metastasis." (PMID 36046433, 2021). "STAT3 activation was associated with a decreased UVB-induced apoptotic response and increased leukocyte infiltration and hyperplasia, suggesting a possible link to cancer." (PMID 34679602, 2021). "Additionally, STAT3 signaling is hyperactivated in the majority of human cancers and a well-established intrinsic pathway driving inflammation, cellular transformation, survival, proliferation, invasion, angiogenesis, metastasis, and immune evasion in cancer." (PMID 33990540, 2021). "Although the downstream targets of miR-519a-3p, such as STAT3/Bcl2, have been well-studied in cancer biology, its upstream regulators remain largely unknown." (PMID 34867700, 2021). "Furthermore, the product of the viral gene UL111A (cmvIL-10) can bind to the IL-10 receptor and induce STAT3 activation and has been detected in different types of cancers." (PMID 34070716, 2021). "Similarly, previous studies have also demonstrated the presence of this IL-6/STAT3 feedback loop in other types of cancer." (PMID 34638305, 2021). "The transcription factor STAT3 is vital for cancer cell survival and proliferation." (PMID 34299488, 2021). "Moreover, it is known that AnxA1 regulates the nuclear localization of EGFR and, as a consequence, it can promote immune evasion by favoring the EGFR/STAT3 transcriptional activities in cancer cells." (PMID 34571894, 2021). "In fact, phosphorylated STAT3 in cancer was mostly reported as a cancer promoter, but some studies indicated that it may also act as a suppressor under certain conditions." (PMID 34679602, 2021). "STAT3 promotes cell proliferation and survival in many types of cancer cells." (PMID 33839684, 2021). "JAK2 is known to stimulate STAT3 phosphorylation on tyrosine Tyr705 in many cancer cells." (PMID 33995073, 2021). "Molecular facts involved in SCLC may also the targets for treatment STAT3 regulates inflammation, immunity and metastasis in cancer." (PMID 33535997, 2021).
cancer (continued). "The results of our study indicate that IL-6/STAT3 signaling induces and promotes cancer metastasis." (PMID 33500736, 2021). "IL-11 facilitated cancer cell chemoresistance via IL-11R/STAT3 signalling." (PMID 33671869, 2021). "With hyper- and sustaining-activation in over 70% of human cancers, STAT3 is widely considered as an oncogene and therapeutic target in various types of cancers, and a series of chemicals or targeted biomacromolecules have been employed in clinical cancer treatment." (PMID 34502195, 2021). "Activated STAT3 is a potential molecular target in the management of numerous cancers." (PMID 34376200, 2021). "Activation and interaction of STAT3 and NF-κB signaling in cancers has been investigated extensively and STAT3 activation could prolong NK-κB continuous activation." (PMID 34405002, 2021). "Increasing evidence indicates that STAT3 inhibition in cancer cell lines could trigger growth arrest or apoptosis by PT." (PMID 34771150, 2021). "The strategy of inhibiting ERK 1/2, AKT and STAT3 activity is extensively studied in various cancers, as these proteins are believed to be essential in overcoming the invasiveness and chemoresistance of cancer cells." (PMID 33478150, 2021). "The inhibition of TrxR1 blocks STAT3 activity and induces cancer cell death." (PMID 34906147, 2021). "The activity of mitogen-activated protein kinases (MAPKs), phosphoinositide 3-kinase (PI3K)/Akt, TNFα/NF-κB, IL6/STAT3, and other pathways, along with many pathway-related proteins, may induce a dual effect of NO on cancer cells." (PMID 34356634, 2021). "For subsequent study, we have chosen three proteins, ERK 1/2, AKT and STAT3, as their phosphorylation level is one of the highest and they are known to participate in intracellular signaling pathways involved in cancer cells’ growth, survival and response to cytotoxic agents." (PMID 33478150, 2021). "This phosphorylation enables the activated STAT3 pathway to drive PD‐L1 expression in cancers." (PMID 33455075, 2021). "Despite these data and the knowledge that most cancers have increased expression of STAT3, no molecular mechanism has previously linked STAT3 to involvement in the onset of mitosis." (PMID 32797246, 2021). "Besides suppressing toxic immune responses, STAT3 functions as an oncogene in malignant cells and is a key factor that links inflammation and cancer." (PMID 35048056, 2021). "β-caryophyllene has been found to hinder metastasis, cause a reduction in oncogene and protein expression of cancer cells while upregulating genes and proteins that destroy cancer cells through the modulation of pathways such as MAPK, PI3K, AKT, mTOR, S6K1, and STAT3." (PMID 35009027, 2021). "Similarly, a cancer cell spheroid invasion assay in a 3D setting showed that STAT3 silencing markedly decreased the invasion of HepG2 cells overexpressing KIAA1217." (PMID 35008530, 2021). "Moreover, IL-6 secreted by activated fibroblasts in cancer stroma induces EMT of gastric cancer cells via JAK2/STAT3." (PMID 34207510, 2021). "The proliferation and invasion of several cancers could be explained by STAT3 activation and cyclin D1 overexpression." (PMID 35003089, 2021). "Furthermore, inhibition of JAK2/STAT3 signaling pathway using WP1066 effectively suppressed cancer cell proliferation, resistance to cisplatin, and DDR." (PMID 34496932, 2021). "In addition, the cell viability of these cell lines significantly decreased after STAT3 knockdown compared to the control, which suggested that STAT3 plays an important role in promoting cancer cell growth." (PMID 33753770, 2021). "This information suggests targeting IL-6/STAT3/cyclin D axis in cancers with low PDS5B might provide a novel therapeutic approach." (PMID 34070827, 2021). "The aberrantly activated form of STAT3 promotes tumorigenesis in many cancers, including TNBC." (PMID 34638797, 2021).